PIK3IP1 (phosphoinositide-3-kinase interacting protein 1)
Description:
Negative regulator of hepatic phosphatidylinositol 3-kinase (PI3K) activity.
Synonyms: HGFL; MGC17330; TrIP; hHGFL(S)
Tractability: Antibody: UniProt places it where antibodies can reach, with high confidence; UniProt predicts a signal peptide or a membrane-spanning region; its Gene Ontology location is reachable by antibodies, with medium confidence. PROTAC: ubiquitination databases record sites on it; its protein half-life has been measured.
Gene: Protein-coding gene on chromosome 22 (31,281,594 to 31,292,534, reverse strand). Ensembl gene ENSG00000100100.
Subcellular location: Cell membrane
Gene Ontology:
Molecular function: phosphatidylinositol 3-kinase inhibitor activity; protein binding; endopeptidase activity; signaling receptor binding
Biological process: negative regulation of phosphatidylinositol 3-kinase/protein kinase B signal transduction
Cellular component: plasma membrane
Genetic constraint (gnomAD): Loss-of-function variants: 28 observed, 27.06 expected, observed/expected ratio (o/e) 1.03, 90% interval 0.77 to 1.42. The upper end of that interval is the gene's LOEUF score, 1.42, which puts it in group 5 of 6, group 1 being the genes least tolerant of losing a copy. Missense variants: 322 observed, 296.31 expected, observed/expected ratio (o/e) 1.09, 90% interval 0.99 to 1.19. Synonymous variants: 156 observed, 126.36 expected, observed/expected ratio (o/e) 1.23, 90% interval 1.08 to 1.41.
Homologues: Orthologues: chimpanzee PIK3IP1 (99% identical), macaque PIK3IP1 (96% identical), pig PIK3IP1 (87% identical), rabbit PIK3IP1 (84% identical), dog PIK3IP1 (83% identical), guinea pig PIK3IP1 (79% identical), mouse Pik3ip1 (79% identical), rat Pik3ip1 (74% identical), zebrafish pik3ip1 (46% identical), tropical clawed frog pik3ip1 (36% identical), Drosophila melanogaster CG11664 (13% identical), Drosophila melanogaster CG31205 (13% identical), and 9 more. Paralogues in human: HABP2 (22% identical), MST1 (21% identical), HGF (18% identical), GZMA (13% identical), GZMK (11% identical).
Diseases named in the same sentence as PIK3IP1 in open-access papers:
PIK3IP1 is named in the same sentence as 34 diseases in open-access papers, as found by Europe PMC text mining. Sharing a sentence is not in itself a finding about the gene and the disease. The quoted sentences say what the papers report.
hepatocellular carcinoma (5 papers, 2020 to 2022). A malignant tumor that arises from hepatocytes. "Pik3ip1 is a negative regulator of Pi3k and a tumor suppressor in a mouse model of hepatocellular carcinoma." (PMID 35468745, 2022). "The inhibition of PI3Ks through PIK3IP1 has been shown to inhibit DNA synthesis and the survival of hepatocytes and to suppress the development of hepatocellular carcinoma." (PMID 35453756, 2022). "For example, miR-19a-3p was reported to promote the proliferation of hepatocellular carcinoma cells via regulation of the PIK3IP1/AKT pathway; however, another study reported that miR-19-3p induces colorectal cancer cell apoptosis by repressing the expression of Fas cell surface death receptor." (PMID 34429758, 2021). "Taken together, these experiments support the model in which SAMD1 acts as a negative regulator of PIK3IP1 in wild-type HepG2 cells, which is a negative regulator of PI3K in hepatocellular carcinoma cells." (PMID 35453756, 2022).
cardiac hypertrophy (3 papers, 2015 to 2022). "The finding that Pik3ip1 deficiency induces cardiac hypertrophy through PI3K/AKT activation led us to examine whether Pik3ip1 overexpression has the opposite effect." (PMID 25826393, 2015). "Collectively, the results suggest that Pik3ip1 deficiency activates the PI3K pathway and induces cardiac hypertrophy." (PMID 25826393, 2015). "Collectively, our study led to a novel finding that the PI3K binding partner, Pik3ip1, plays an important role in physiological cardiac hypertrophy through the PI3K pathway." (PMID 25826393, 2015). "We previously reported the function of PIK3IP1 in physiological cardiac hypertrophy, but the function of PIK3IP1 in the heart under pathological conditions remained unknown." (PMID 35883611, 2022). "In the present study, the effects of Pik3ip1 on cardiac hypertrophy were examined." (PMID 25826393, 2015). "However, adenovirus-mediated overexpression of Pik3ip1 attenuated PI3K-mediated cardiac hypertrophy." (PMID 25826393, 2015). "Approximately 35% knockdown of Pik3ip1 was sufficient to induce myocardial hypertrophy." (PMID 25826393, 2015). "Our findings that Pik3ip1 expression levels modulate cardiomyocyte hypertrophy through the PI3K pathway, led us to test Pik3ip1 expression levels in mouse models of cardiac hypertrophy." (PMID 25826393, 2015). "These two datasets appear to have in common phosphoinositide-3-kinase interacting protein 1 (PIK3IP1), a negative regulator of PI3K and physiological, but not pathological cardiac hypertrophy." (PMID 29556499, 2018).
autoimmune disease (2 papers, 2024 to 2025). A disorder resulting from loss of function or tissue destruction of an organ or multiple organs, arising from humoral or cellular immune responses of the individual to their own tissue constituents. "Other studies have highlighted the importance of Pik3ip1 in the treatment of autoimmune diseases." (PMID 41378839, 2025). "In the field of autoimmune diseases, PIK3IP1 is considered a key regulatory factor." (PMID 38571624, 2024).
autoimmune myasthenia gravis (2 papers, 2019 to 2026). "Although PIK3IP1 encodes a protein involved in the regulation of immunological signaling and has been implicated in autoimmune myasthenia gravis, this association most likely reflects a distinct pathogenic mechanism from CMS." (PMID 41575592, 2026). "By comparing transcriptome of thymoma with and without myasthenia gravis, we found that 5 genes (PNISR, CCL25, NBPF14, PIK3IP1 and RTCA) were upregulated more than 2-fold, and that more than 30 genes were downregulated more than 2-fold." (PMID 30787364, 2019).
bladder cancer (2 papers, 2022 to 2025). "Studies show that PIK3IP1 protein is upregulated in ARID1A‐deficient bladder cancer cells and inhibits the PI3K signalling pathway." (PMID 39779467, 2025). "To determine if PIK3IP1 upregulation is necessary and sufficient for GSK-126 sensitivity in ARID1A-deficient bladder cancer cells, we generated an array of dual ARID1A/PIK3IP1 stable knockdown cells and ARID1Akd/PIK3IP1 stable overexpression cells." (PMID 35852858, 2022). "PIK3IP1 upregulation is necessary and sufficient for GSK-126–mediated cell death in ARID1A-deficient bladder cancer cells." (PMID 35852858, 2022). "Inhibition of EZH2 in ARID1Adef bladder cancer cells results in upregulation of PIK3IP1, an endogenous inhibitor of PI3K signaling." (PMID 35852858, 2022). "However, while PIK3IP1 protein levels are increased in response to GSK-126 in ARID1Adef cells in both OCCC and bladder cancer, the effects of ARID1A levels on PIK3IP1 expression are opposite between the cell types." (PMID 35852858, 2022).
Cerebral ischemia (2 papers, 2020 to 2022). Restriction of arterial blood supply to the brain associated with insufficient oxygenation to support the metabolic requirements of the tissue. "Consistently, the overexpression of PIK3IP1 is relevant in rat models of cerebral ischemia induced via MCAO (middle cerebral artery occlusion)." (PMID 36077416, 2022). "Western blot assay was carried out to detect the downstream genes of PI3K/Akt pathway in the cerebral ischemia injury, including PIK3IP1, PI3K, p-PI3K, Akt, and p-Akt." (PMID 33082912, 2020). "Our finding indicated that RiPerC inhibited the MCAO-induced expression of PIK3IP1 through upregulated miR-98, thereby reducing the apoptosis induced by PIK3IP1 through the PI3K/AKT signaling pathway, thus reducing the cerebral ischemia-reperfusion injury." (PMID 33082912, 2020). "Therefore, our finding indicates that RiPerC inhibited the expression of PIK3IP1 by upregulated miR-98, thereby reducing the apoptosis induced by PIK3IP1 through the PI3K/AKT signaling pathway, thus reducing the cerebral ischemia-reperfusion injury." (PMID 33082912, 2020).
leukemia (2 papers, 2021 to 2022). A malignant (clonal) hematologic disorder, involving hematopoietic stem cells and characterized by the presence of primitive or atypical myeloid or lymphoid cells in the bone marrow and the blood. "In summary, the combinatorial blockade of the EZH2 and BCL-2 shows a great synergistic anti-leukemia effect through upregulated PIK3IP1 and downregulated c-KIT." (PMID 36232694, 2022).
osteosarcoma (2 papers, 2019 to 2020). A usually aggressive malignant bone-forming mesenchymal neoplasm, predominantly affecting adolescents and young adults. "CCAT1 is upregulated in osteosarcoma tissues and cells and participates in the proliferation and migration of osteosarcoma by regulating mir-148a/phosphatidylinositol 3-kinase interaction protein 1 (pik3ip1) signal pathway." (PMID 32883200, 2020).
ovarian carcinoma (2 papers, 2018 to 2019). A malignant neoplasm originating from the surface ovarian epithelium. "In certain ovarian cancer cells, the noted growth inhibitory effects of EHZ2 inhibition are attributed to increased levels of phosphoinositide-3-kinase interacting protein 1(PIK3IP1) which antagonizes the cell survival signaling." (PMID 31426393, 2019).
breast carcinoma (1 paper, 2020). "In addition, by analyzing immune T-cell signature genes, we showed PIK3IP1 upregulated in HIV-positive breast cancer samples." (PMID 33194615, 2020).
cutaneous melanoma (1 paper, 2022). A primary melanoma arising from atypical melanocytes in the skin. "In the cutaneous melanoma cell lines, MEL 04.01 and MEL 06.24, Nutlin-3 treatment increased significantly CDKN1A, CYFIP2 and PTCHD4 expression, whereas PIK3IP1 and MXD4 levels do not or hardly change." (PMID 36139642, 2022).
diabetic retinopathy (1 paper, 2023). "We also found that targeting PIK3IP1 can specifically inhibit microglial activation towards the M1 phenotype, which is a potential strategy for treatment of diabetic retinopathy." (PMID 37550343, 2023).
gastric cancer (1 paper, 2024). A primary or metastatic malignant neoplasm involving the stomach. "In addition, PIK3IP1 is highly expressed in PI3Kα inhibitor-sensitive gastric cancer cells and can be used as a marker to detect the anti-cancer activity of PI3Kα inhibitor." (PMID 38658954, 2024).
Insulin resistance (1 paper, 2024). Increased resistance towards insulin, that is, diminished effectiveness of insulin in reducing blood glucose levels. "Functional enrichment analysis revealed that upregulated genes were involved in PI3K binding (e.g. PIK3IP1, IRS2, ATP1A1), insulin resistance and FOXO signalling genes while downregulated genes were overrepresented by metabolic and immune processes." (PMID 39593143, 2024).
ischemic heart diseases (1 paper, 2022). "Our present study of PIK3IP1 that shows the functional anti-ischemic role in the heart will be immensely beneficial to gene therapy efforts for ischemic heart diseases." (PMID 35883611, 2022).
lung adenocarcinoma (1 paper, 2017). A carcinoma that arises from the lung and is characterized by the presence of malignant glandular epithelial cells. "Indeed, a negative correlation between PIK3IP1 expression and Ras mutation status in human colorectal and lung adenocarcinomas were observed." (PMID 29259156, 2017).
myocardial infarction (1 paper, 2022). Gross necrosis of the myocardium, as a result of interruption of the blood supply to the area, as in coronary thrombosis. "Interestingly, PIK3IP1 expression was also decreased upon initiation of myocardial infarction, but was reversed with increased duration (unpublished data), further supporting the idea that PIK3IP1 is closely related to the pathophysiological condition of the heart." (PMID 35883611, 2022).
skin cancer (1 paper, 2022). "PIK3IP1 was reported as a negative regulator for T-cell immunity, and OXNAD1 mutation was reported to be linked to skin cancer." (PMID 35865544, 2022).
tuberculosis (1 paper, 2018). A chronic, recurrent infection caused by the bacterium Mycobacterium tuberculosis. "Transcriptomics from tuberculosis patients indicate (i) that PIK3IP1 is part of the transcriptomic signature that discriminates tuberculosis from other inflammatory infections and diseases and (ii) that its expression is downregulated in circulating neutrophils in comparison to healthy controls." (PMID 30065729, 2018).
cancer (12 papers, 2015 to 2024). A tumor composed of atypical neoplastic, often pleomorphic cells that invade other tissues. "Using an EZH2 inhibitor reinforces the synthetic lethal strategy by upregulating PIK3IP1 in AIRID1A-mutated cancers." (PMID 36185333, 2022). "Changes in the expression of numerous genes (CDKN1A, SMAD3, MLH1 and PIK3IP1) caused by mutations in ARID1A contribute to the development of cancer and have been linked to the PI3K/AKT pathway in cell translocation, which was highly likely to become a therapeutic target for OC." (PMID 37525498, 2023). "However, the regulatory mechanism underlying PIK3IP1 gene suppression by Ras in cancer cells remains unknown." (PMID 31900384, 2020). "In this case, the assumption made for FINC, APOB and PLTP would be the opposite: cancer cells eliminate more PIK3IP1 protein in the urine, as a mechanism to down-regulate its expression, in order to survive." (PMID 31963743, 2020). "To test if restoring PIK3IP1 expression reversed the effects of Ras, we transduced PIK3IP1 into A549 Ras-mutant cancer cell using a Lenti-X Tet-On Inducible Expression system." (PMID 31900384, 2020). "We previously reported that activated Ras suppresses PIK3IP1 expression to positively regulate the PI3K pathway in cancer cells." (PMID 31900384, 2020). "We previously found that PIK3IP1 mRNA expression level was significantly downregulated in most Ras/Raf-mutant cancer cells." (PMID 31900384, 2020). "Following S2101 exposure the PIK3IP1 mRNA expression level was upregulated from 3–10-fold in multiple Ras- or Raf-mutant cancer cells." (PMID 31900384, 2020). "All these observations suggested that PIK3IP1 is a direct target of miR-19a-3p in Huh7 cancer cells." (PMID 32201518, 2020). "The selectivity of a131 for Ras-mutant cancer cells is due to the ability of activated Ras to suppress PIK3IP1 transcription." (PMID 31900384, 2020). "Pharmacological inhibition of LSD1 restored PIK3IP1 expression in multiple Ras- or Raf-mutant cancer cells." (PMID 31900384, 2020). "Recent studies have reported that transcription factors such as Foxo3 and Cux1 are involved in the regulation of Pik3ip1 expression in brain tissue and cancer cells." (PMID 25826393, 2015). "In summary, oncogenic Ras through the MEK/ERK pathway activates LSD1 and increases the binding of the LSD1 corepressor complex to the PIK3IP1 promoter and enhancer to decommission PIK3IP1 activity, which in turn reactivates the PI3K pathway in Ras mutated cancer." (PMID 31900384, 2020). "To determine whether miR-19a-3p regulates PIK3IP1 expression in Huh7 cancer cells, we evaluated the PIK3IP1 expression level in miR-19a-3p OE and miR-19a-3p KD groups." (PMID 32201518, 2020). "In addition, the PIK3IP1 mRNA levels are significantly lower in Ras/Raf-mutant cancer cells." (PMID 31900384, 2020). "Using Ras-activated cancer cells and clinical samples from patients with colorectal and lung adenocarcinomas, we have described the underlying mechanism for cross-activation, positive cross-talk, between the Ras/Raf/MEK/ERK and PI3K/AKT/mTOR pathways through PIK3IP1 suppression." (PMID 31900384, 2020). "In this regard, further elucidation of how PI3K activity is regulated by more subtle modulators of the pathway like PIK3IP1 and BCAP may lead to novel approaches to tune PI3K activity for enhancement or inhibition of lymphocyte responses to infection or cancer." (PMID 33024547, 2020). "Moreover, PIK3IP1 mRNA levels were not only considerably lower in Ras-mutant and Raf-mutant cancer cells compared with normal cells, but a131-mediated and a166-mediated induction of PIK3IP1 was also significantly attenuated in these cancer cells, unlike normal cells." (PMID 29259156, 2017).
tumor (10 papers, 2015 to 2026). "Loss of PIK3IP1 increased lactate production and histone H4K12 lactylation (H4K12la), coinciding with upregulation of PD-L1 and CSF1 and enhanced tumor immunosuppressive features." (PMID 42206447, 2026). "Correspondingly, tumor-associated target genes including ALDH3A2, SEMA3F, MAP4K5, and TRIP13 were upregulated, whereas PIK3IP1, AGO2, MMP2, and RALBP1 were suppressed." (PMID 41897301, 2026). "Of these genes, one tumor suppressor, PIK3IP1, was particularly notable, as it attenuates PI3K/AKT/mTOR signaling through a direct inhibition of PIK3CA/p110α." (PMID 35852858, 2022). "Recent studies suggest that PIK3IP1 may act as a tumor suppressor to regulate tumor cell function and anti-tumor immune activity." (PMID 38658954, 2024). "Finally, these data demonstrate that the role of PIK3IP1 in the sensitivity of ARID1Adef cells to EZH2 inhibitors may be shared among multiple tumor types." (PMID 35852858, 2022). "Of note, the regulation of PIK3IP1 is dependent on EZH2 methyltransferase and inhibition of EZH2 activity combined with loss of ARID1A expression is synthetically lethal, highlighting a potential therapeutic vulnerability through the use of EZH2 inhibitors in this tumour." (PMID 33053751, 2020). "PIK3IP1 is a recently discovered negative regulator of PI3K, which can bind p110 and prevent its activation by p85, thereby down-regulating PI3K signaling to inhibit tumor growth." (PMID 38658954, 2024). "Moreover, the expression of PIK3IP1, a negative regulator of PI3K and suppressor of tumor development, increases after EphA6 knock-down." (PMID 26041887, 2015).
cardiovascular diseases (2 papers, 2022 to 2024). "Therefore, PIK3IP1 plays a regulatory role in cardiac protection and the occurrence and progression of cardiovascular diseases." (PMID 38571624, 2024).
PIK3IP1 also shares sentences with these, for which no sentence is quoted: autoimmune hepatitis (1 paper); colorectal cancer (1); cystic fibrosis (1); depression (1); esophageal squamous cell carcinoma (1); hypertrophy (1); infection (1); lung diseases (1); mantle cell lymphoma (1); Sepsis (1); squamous cell lung carcinoma (1); thymoma (1).